TMPRSS2 (transmembrane serine protease 2)
Diseases named in the same sentence as TMPRSS2 in open-access papers (continued):
Sharing a sentence is not in itself a finding about the gene and the disease.
COVID-19 (continued). "This variant has been reported to be possibly associated with susceptibility to coronavirus disease 2019, and it was suspected that rs469390-A expression in the lung might be associated with the high TMPRSS2 expression levels and further associated with the higher susceptibility to the disease." (PMID 37138773, 2023). "The present study investigated the association between the TMPRSS2 genotype and the severity of the Coronavirus disease 2019 (COVID-19) in Iranian patients." (PMID 36795725, 2023). "They stated that ACE1rs1799752 minor allele I and ACE2rs2285666A are associated with decreased COVID-19 severity while TMPRSS2 rs12329760 is linked to severe COVID-19 outcomes." (PMID 36743382, 2023). "The ACE2, NRP1 and the transmembrane serine protease 2 (TMPRSS2) were detected in human nerves near the medulla, which is likely to cause the loss of taste in COVID-19 patients, and other CNS regions." (PMID 37380640, 2023). "This risk should be evaluated on an individual basis, considering ACE2 and TMPRSS2 expression, existing literature regarding the susceptibility to infection, and single cell RNA sequencing data of COVID-19 patients." (PMID 36453030, 2023). "The present prospective cohort study aims to assess the association between the ACE-1 rs4343, ACE-2 rs908004 and TMPRSS2 rs12329760 genes and the COVID-19 clinical severity in Egyptian patients." (PMID 37426824, 2023). "We also observed a trend for the association between the rs4290734 G-allele residing in the TMPRSS2 gene (β = 1.76, p = 0.078) and the presence of neurological symptoms in our cohort of mild COVID-19 cases." (PMID 36675784, 2023). "Considering the pathogenesis of COVID-19 it is important to underline the role of the ACE-2 receptor associated with transmembrane serine protease 2 (TMPRSS2) as a molecular key point for the virus to infect human cells." (PMID 36831150, 2023). "Considering the role of this variant in the entry of the virus into the host cell, we aimed to investigate the association between the TMPRSS2 rs12329760 variant and the severity of COVID-19 in the Iranian population." (PMID 36795725, 2023). "These SNPs were chosen based on data from an Egyptian cohort which showed that rs2285666 (ACE2) and rs12329760 (TMPRSS2) were significantly associated with the severity of COVID-19 and select co-morbidities." (PMID 37761938, 2023). "Numerous studies examined expression levels and tissue distribution of TMPRSS2 in comorbidities that have been associated as risk factors for severe COVID-19 outcomes." (PMID 37208193, 2023). "Further studies involving larger sample size and more diverse populations should be conducted to provide better understanding of the relationship between the ACE-1, ACE-2 and TMPRSS2 polymorphism and COVID-19 disease severity." (PMID 37426824, 2023). "Several studies have investigated the association of rs2285666 (ACE2) and rs12329760 (TMPRSS2) with COVID-19 severity." (PMID 37761938, 2023). "Among genetic markers, we found that G carriers of TMPRSS2 (rs2070788) have an increased risk (p = 0.02; OR = 3.37, 95% CI 1.18–9.60) of severe COVID-19 compared to those with A/A genotype." (PMID 36969980, 2022). "In fact, a substantial association between the COVID-19 case fatality and a nonsynonymous mutation in the TMPRSS2 V197M allele has been demonstrated." (PMID 35193695, 2022). "In the literature included, we isolated 10 SNPs and 21 mutations in the ACE2 gene and 13 SNPs and 12 mutations in the TMPRSS2 gene potentially related to COVID-19." (PMID 35193695, 2022). "The frequencies of the TMPRSS2 variant alleles c.331G > A, c.23G > T, and c.589G > A in an Italian cohort of COVID-19 patients were demonstrated to vary significantly from the corresponding allele frequencies in the GnomAD database." (PMID 35193695, 2022). "Here, we found the role of TMPRSS2 (rs2070788) G allele carriers as an interesting and simple way to classify severe COVID-19 patients." (PMID 36969980, 2022).
COVID-19 (continued). "In particular, a total of 7,843 co-expressed genes of the TMPRSS2 associated with PRAD whereas the number of co-expressed genes related to COVID-19 was 7,231." (PMID 36239108, 2022). "This is the first study evaluating the role of polymorphisms in TMPRSS2 in the context of COVID-19 in a Latin American population." (PMID 36423166, 2022). "The frequencies of TMPRSS2 variants rs12329760 and rs2298659 are associated with the severity of COVID-19, especially in young men and older women." (PMID 35165525, 2022). "The SARS-CoV-2 coronavirus, which causes COVID-19, uses a viral surface spike protein for host cell entry and the human cell-surface transmembrane serine protease, TMPRSS2, to process the spike protein." (PMID 35412356, 2022). "In line with this, it has also been suggested that ACE2 and TMPRSS2 DNA polymorphisms are associated with COVID-19 susceptibility and clinical outcome." (PMID 35532162, 2022). "The aim was to investigate the association between TMPRSS2 gene polymorphisms and the risk of death in hospitalized patients with COVID-19." (PMID 36423166, 2022). "Despite its negligible effects on the expression of ACE2 and TMPRSS2 in endothelial cells, cigarette smoking is still associated with increased risk of severe COVID-19." (PMID 35021853, 2022). "There was an increase in the expression of genotype frequencies of ACE2 rs2285666 and TMPRSS2 rs1232976 (TT), (CT + TT), and (T) allele in severe COVID-19 group compared to control and mild groups." (PMID 35996506, 2022). "Among all, the specific variants associated with HLA, ACE2, and TMPRSS2 have significant contribution in modulating the COVID-19 severity." (PMID 36072602, 2022). "This variant has been widely studied in the context of COVID-19 due to its functional effect that causes a decrease in the proteolytic activity of TMPRSS2." (PMID 36423166, 2022). "In conclusion, the T allele of the common TMPRSS2 variant rs12329760 confers a reduced risk of severe COVID-19." (PMID 35104687, 2022). "Some studies have correlated the T (A) allele of the ACE2 rs2285666 and of TMPRSS2 rs12329760 SNPs with lower severity of COVID-19 in an Indian population." (PMID 36360172, 2022). "This review included 33 articles with 33,923 patients from 160 regions and 50 countries (principally Caucasians) and identified 12 TMPRSS2 polymorphisms associated with COVID-19." (PMID 36146782, 2022). "Other genes such as ACE2 and TMPRSS2 have shown an association with the need of oxygen therapy during COVID-19 as well as predicting disease severity." (PMID 35186993, 2022). "Nevertheless, we demonstrated an association between the T allele of the TMPRSS2 rs12329760 polymorphism and protection against the most severe form of COVID-19." (PMID 35793369, 2022). "Collectively, these results indicate that the genetic variation in TMPRSS2, which is common in East Asians, is one of the molecular determinants of COVID-19 susceptibility." (PMID 36532428, 2022). "Seven variants (rs3787946, rs9983330, rs12329760, rs2298659, rs2298661, rs9985159 and rs756036675) within TMPRSS2 were identified to be associated with severe COVID-19." (PMID 36204639, 2022). "The detailed analysis of the COVID-19 Host Genetic Initiative (HGI) data revealed an important link between the TMPRSS2 rs12329760 polymorphism and disease severity." (PMID 36457338, 2022). "The current study assessed the influence of genetic polymorphisms modulating TMPRSS2 expression on the risk of death in 402 hospitalized patients with COVID-19." (PMID 36423166, 2022). "In conclusion, the C allele of the common TMPRSS2 rs12329760 polymorphism confers an increased risk of COVID-19 mortality rate." (PMID 36457338, 2022). "In the present study, we conducted expression, mutation, and prognostic analyses for the TMPRSS2 gene in pan-cancers and in COVID-19-infected lung tissues." (PMID 36364238, 2022).
COVID-19 (continued). "When well-characterized cohorts of asymptomatic/pauci symptomatic COVID-19 patients become available, it will be possible to further investigate the role of TMPRSS2 variant rs12329760 on Sars-Co-V2 infection." (PMID 35104687, 2022). "Genotype frequencies TMPRSS2 (rs12329760) TT and CT + TT, and allele frequency T showed a significant increase in the severe COVID-19 group in the current study." (PMID 35996506, 2022). "A comprehensive comparative genetic analysis of 81,000 human genomes suggests the association of TMPRSS2 polymorphisms with COVID-19 susceptibility." (PMID 36146782, 2022). "It was suggested that more genotyping studies of COVID-19 was needed to explore the contribution of TMPRSS2 variants to clinical outcomes." (PMID 36204639, 2022). "Other variants in ACE2 and TMPRSS2 affect the expression of the receptors related to COVID-19 and have been associated with disease susceptibility and risk factors." (PMID 35889989, 2022). "To date, most in silico reports have conducted to investigate the impact of polymorphisms in the TMPRSS2 gene on COVID-19." (PMID 36457338, 2022). "Because TMPRSS2 plays an important role in the pathogenesis of COVID-19, the activity of the gene encoding this protein is associated with susceptibility to the virus and the severity of the disease." (PMID 35327350, 2022). "The role of structural and regulatory variations of TMPRSS2 in susceptibility to COVID-19 is being actively studied." (PMID 35327350, 2022). "In conclusion, the TMPRSS2 rs12329760 CC genotype was a polymorphism linked to a significantly higher incidence of severe COVID-19." (PMID 36457338, 2022). "TMPRSS2 rs12329760 is a common variant associated with a significantly decreased risk of severe COVID-19." (PMID 35104687, 2022). "In the present study, we analyzed the distribution of four TMPRSS2 polymorphisms in a Mexican cohort of patients with COVID-19." (PMID 36146782, 2022). "Although high ACE2 and TMPRSS2 expression levels are associated with a severe prognosis of COVID-19, in this study, we evaluated specific clinical symptoms of the disease." (PMID 36250059, 2022). "We demonstrated for the first time that older patients carrying the rs2070788 GG genotype, which is associated with high TMPRSS2 expression in human lung tissue, had a higher risk of death by COVID-19." (PMID 36423166, 2022). "Herein, we conducted expression, mutation, and prognostic analyses for the TMPRSS2 gene in pan-cancers as well as in COVID-19-infected lung tissues." (PMID 36364238, 2022). "We found that G carriers (TMPRSS2 in rs2070788) have an increased risk (p = 0.02; OR = 3.37, 95% CI 1.18–9.60) of having severe COVID-19 compared to those with AA." (PMID 36969980, 2022). "With the COVID-19 pandemic, several studies investigated the potential roles of TMPRSS2 variants in susceptibility to COVID-19 through in silico studies using public genomic databases." (PMID 36423166, 2022). "Studies evaluating the role of SNPs in TMPRSS2 with the risk of death in hospitalized patients with COVID-19 are scarce, usually with a small sample size, retrospective, and performed in Asian populations." (PMID 36423166, 2022). "In the present study, we investigated the role of rs2070788 and rs12329760 polymorphisms in TMPRSS2 with the risk of death in patients with COVID-19 followed up in two referral centers in the Northeast Region of Brazil." (PMID 36423166, 2022). "Several reports revealed an association between the variable expression of ACE2 and TMPRSS2 in different tissues across individuals with COVID-19 severity/fatality variations." (PMID 36560732, 2022). "This study provides useful information for the identification of patients at risk of developing a severe form of COVID-19, and encourages the usage of drugs affecting the expression of TMPRSS2 or inhibiting protein activity." (PMID 33921689, 2021).
COVID-19 (continued). "Since the lung is considered one of the primary target locations of SARS-CoV-2, it is argued that TMPRSS2 expression levels in pulmonary cells change across different populations, with consequent variable susceptibility to COVID-19." (PMID 34399734, 2021). "For example, endometrium carries low susceptibility to COVID-19 due to the low expression of TMPRSS2 and ACE2." (PMID 34016183, 2021). "A more recent study has highlighted the correlation between a TMPRSS2 variant with a high number of cases and/or deaths of COVID-19 observed in different countries." (PMID 34201505, 2021). "Since elevated expressions of ACE-2 and TMPRSS2 are associated with higher mortality risk from COVID-19, the latter two receptors have been investigated to develop potential agents effective to interfere with the replication of SARS-CoV-2." (PMID 34399734, 2021). "The sex discordance in COVID-19 outcomes is potentially link to androgen-induced expression of TMPRSS2 and/or ACE2 in pulmonary tissues which increases susceptibility or severity in males." (PMID 34948113, 2021). "Abnormalities in ACE2 expression in patients with hypertension and obesity and abnormalities in TMPRSS2 expression in individuals exposed to high levels of androgens have been shown to be risk factors for COVID-19." (PMID 33477294, 2021). "In particular, in-depth analysis of available data from the COVID-19 Host Genetic Initiative (HGI) suggested a significant association between TMPRSS2 gene polymorphism rs12329760 with severe/hospitalised COVID-19." (PMID 34001248, 2021). "As for the p.Val160Met (rs12329760) polymorphism in TMPRSS2, it provides potential explanations for differences in COVID-19 genetic susceptibility as well as for risk factors, including high risk male and cancerous patients." (PMID 34834033, 2021). "ACE2 and TMPRSS2 DNA polymorphisms have been shown to be strongly associated with the susceptibility, severity, and clinical outcomes of COVID-19." (PMID 34016183, 2021). "SARS-CoV-2 entry into ACE2, which is upregulated in many risk factors predisposing to severe COVID-19, is facilitated by TMPRSS2-induced activation of the S protein via its serine protease activity." (PMID 34501332, 2021). "Our finding indicates a correlation between polymorphism in the gene encoding the virus receptor complex, i.e. TMPRSS2, and COVID-19 severity." (PMID 34001248, 2021). "Unique but prevalent polymorphisms (including p.Val160Met(rs12329760)) in TMPRSS2 have the potential to causedifferential genetic susceptibility to COVID-19." (PMID 34707899, 2021). "While these data needs validation in larger cohorts, they provide support to the association between androgen control of TMPRSS2 expression and risk of COVID-19." (PMID 34925228, 2021). "This study revealed the high expression of the SARS-CoV-2 receptors, ACE2 and TMPRSS2, at resection margins of lung cancer survivors and its possible relationship with the higher susceptibility of these patients to COVID-19." (PMID 34094930, 2021). "Some known variables of COVID-19 predisposition and disease severity are correlated with TMPRSS2 expression pattern." (PMID 34336361, 2021). "We genotyped 95 patients with COVID-19 hospitalised in Dr Soetomo General Hospital and Indrapura Field Hospital (Surabaya, Indonesia) for the TMPRSS2 p.Val160Met polymorphism." (PMID 34001248, 2021). "In summary, this is the first study to demonstrate a possible association between TMPRSS2 p.Val160Met polymorphism and higher viral load in COVID-19 patients." (PMID 34001248, 2021). "Genetic determinants of susceptibility and/or severity of COVID-19 have been sought in TMPRSS2 in predictive as well as in Whole-Exome Sequencing (WES) studies." (PMID 33921689, 2021). "The prevalent polymorphisms in ACE2 or TMPRSS2 lead to the use of personalized treatments (i.e., hydroxychloroquine and camostat) for COVID-19." (PMID 34016183, 2021).
COVID-19 (continued). "Taken together, the present study shows an association between nasopharyngeal expression of ACE2 and TMPRSS2 genes and the need of oxygen therapy during COVID-19." (PMID 33958627, 2021). "Direct evidence that correlates nasal ACE2 and TMPRSS2 expression with SARS-CoV-2 infection or symptoms associated with COVID-19 is limited." (PMID 34730438, 2021). "Polymorphisms in the TMPRSS2 gene, including p.Val160Met (rs12329760), associated with a genetic predisposition to COVID-19, were found to be more specific for male patients." (PMID 33802310, 2021). "Increased nasopharyngeal ACE2 levels are protective and the TMPRSS2/ACE2 ratio is associated with risk of COVID-19 with prevalent symptomatology (cough, 70.42%; fever, 63.85%; headache, 61.50%; anosmia, 57.28%; myalgia, 55.87%)." (PMID 34948113, 2021). "A review of articles showed individuals with ACE2 polymorphism along with TMPRSS2 are more vulnerable to COVID-19." (PMID 34016183, 2021). "Several variants in ACE2 and TMPRSS2 affecting the expression of the receptors related to COVID-19 have been associated with the disease susceptibility and risk factors." (PMID 33868239, 2021). "Consistently, studies on Italian COVID-19 patients also demonstrated the role of genetic polymorphisms within the TMPRSS2 gene in determining COVID-19 severity." (PMID 34001248, 2021). "We analyzed the TMPRSS2 sequence and correlated the protein variants with the clinical features of a cohort of 1177 patients affected by COVID-19 in Italy." (PMID 33921689, 2021). "We analyzed 131 COVID-19 patients by exome sequencing and examined the genetic variants of TMPRSS2, PCSK3, DPP4, and BSG genes." (PMID 32867305, 2020). "It is thus possible that Italians have enhanced TMPRSS2 activity, and that this results in a higher risk of a more severe form of COVID-19." (PMID 33036180, 2020). "First, high expressions of ACE-2 and transmembrane serine protease-2 (TMPRSS2) in men compared to women would be associated with poorer outcomes with respect to COVID-19." (PMID 33374452, 2020). "In the COVID-19 patient group we identified the rare variant c.331G>A (p.Gly111Arg) localized in the TMPRSS2 gene, with a higher frequency compared to the GnomAD database." (PMID 32867305, 2020). "Together, dysfunctions in the RAAS, ACE2 and TMPRSS2 underlie all major risk factors for severe COVID-19." (PMID 32993622, 2020). "To explore other potential COVID-19 associated hits, we ran both Fluency models with TMPRSS2 as the target on the Selleckchem FDA approved drug library, and ranked hits based on performance in model a." (PMID 32586380, 2020). "By our preliminary study, we observed in the group of COVID-19 patients some differences in the frequencies of the genetic variants located in the two proteases studied, TMPRSS2 and PCSK3, compared to those reported in the GnomAD database." (PMID 32867305, 2020). "The dysregulation of ACE2 has been found to be associated with fluctuations in COVID-19 morbidity and the serine-protease TMPRSS2 has been found to be needed in the priming of the virus in preparation to its entry into the host cell." (PMID 33117174, 2020). "Recently, the expression and function of coding regions and other variants in ACE2 and TMPRSS2 among different populations were systematically analyzed, implying different susceptibilities or responses to COVID-19 in different populations." (PMID 33195331, 2020). "A recently published comparative genetic analysis of approximately 81,000 human genomes across different populations suggested possible associations of coding region variants of ACE2 and TMPRSS2 with COVID-19 susceptibility, severity, and clinical outcomes." (PMID 33092637, 2020). "The expression pattern of ACE2 and TMPRSS2 genes in the CAV1-positive cluster was consistent with the finding that liver cholangiocytes were associated with liver injury in COVID-19 patients." (PMID 33104520, 2020).